BTLA (B and T lymphocyte associated)
Diseases named in the same sentence as BTLA in open-access papers (continued):
Sharing a sentence is not in itself a finding about the gene and the disease.
acute-on-chronic liver failure (2 papers, 2012 to 2024). Acute-on-chronic liver failure (ACLF) is an extreme condition during the natural history of chronic HBV infection, with a relatively high short-term mortality. "B- and T-lymphocyte attenuator (BTLA) levels are increased in patients with hepatitis B virus-related acute-on-chronic liver failure (HBV-ACLF)." (PMID 38418488, 2024). "However, the expression and anatomical distribution of BTLA and its ligand, the herpes virus entry mediator (HVEM), have not yet been determined in cases of HBV-related acute-on-chronic liver failure (HBV-ACLF) patients." (PMID 23067542, 2012).
allergic disease (2 papers, 2012 to 2021). An immune response that occurs following re-exposure to an innocuous antigen, and that requires the presence of existing antibodies against that antigen. "Further analysis is needed to reveal the role of BTLA in the biologic basis of eosinophil-mediated allergic diseases." (PMID 34163466, 2021). "However, the precise mechanism is still unclear and no information on the role of BTLA in allergic diseases in humans is available." (PMID 34163466, 2021).
bladder cancer (2 papers, 2020 to 2021). "The TIMER database analysis revealed that BTLA mRNA expression was lower in bladder cancer (BLCA), colon adenocarcinoma (COAD), lung squamous cell carcinoma (LUSC), rectum adenocarcinoma (READ), and thyroid carcinoma (THCA) compared with adjacent normal tissues." (PMID 32793631, 2020).
breast tumor (2 papers, 2019 to 2025). "To evaluate CD8+ T-cell exhaustion in 4T1 breast tumour-bearing mice, we examined the level of IR mRNAs, including PD-1, TIM-3, BTLA and exhausted T-cell-associated transcriptional factor Foxp1 using reverse transcription quantitative polymerase chain reaction (RT–qPCR)." (PMID 31594465, 2019).
cerebral malaria (2 papers, 2018). A sequestration of Plasmodium falciparum in the brain, which can cause coma and/or seizures. "Of note, genetic variants of BTLA in humans, influence susceptibility to severe chronic hepatitis B, which could influence susceptibility to cerebral malaria." (PMID 30631323, 2018). "Following infection of mice with cerebral malaria-causing P. berghei, both CD4+ and CD8+ T cells in the spleen exhibited increased BTLA expression." (PMID 30631323, 2018). "Consequently, BTLA not only restricts the T cell mediated immunopathology during cerebral malaria but also the protective immunity against a non-lethal infection with P. yoelii by the suppression of phagocytes and B cells." (PMID 30483269, 2018).
Cirrhosis (2 papers, 2024). A chronic disorder of the liver in which liver tissue becomes scarred and is partially replaced by regenerative nodules and fibrotic tissue resulting in loss of liver function. "In conclusion, elevated plasma levels of immune checkpoint proteins BTLA, PD-1, and TIM-3 one year after successful HCV treatment were associated with persistently high liver stiffness five years later, suggesting a potential immunopathological role in cirrhosis after HCV eradication in PWH." (PMID 39742264, 2024). "Surface BTLA, PD-1, and TIM-3 are increased in HCV-infected patients who progressed to cirrhosis and HCC." (PMID 39742264, 2024). "Except for patients with HBV-ACLF, those with alcohol-induced ACLF and cirrhosis showed high expression of BTLA on CD4+ T cells (but not on CD8+ T cells), while patients with primary biliary cholangitis did not exhibit high expression of BTLA (n = 4)." (PMID 38418488, 2024). "Hence, BTLA, PD-1, and TIM-3 could be predictive biomarkers of persistently liver stiffness and serious pathologies derived from cirrhosis, but further studies are needed to corroborate our findings." (PMID 39742264, 2024).
co-infection (2 papers, 2019 to 2024). "Together these data provide new insights into the phenotype of Mtb-specific CD4 T cells in the setting of co-infection with Mtb and HIV and provide rationale for future studies to evaluate the utility of targeting BTLA and HVEM signaling pathways to enhance protective immunity to Mtb." (PMID 31497018, 2019). "Moreover, we found that IL-6 and TNF-α, generally induced by LPS, may promote BTLA expression on CD4+ T cells via the STAT3 and NF-κB signaling, which explains why HBV-ACLF patients with coinfection have elevated BTLA levels." (PMID 38418488, 2024).
endometriosis (2 papers, 2021 to 2024). The growth of functional endometrial tissue in anatomic sites outside the uterine body. "Interestingly, the CALCR and BTLA pathways are present in both endometriosis conditions and CCC but not in healthy tissue, indicating a dysregulation in the calcium pathway and immune checkpoint, respectively." (PMID 39149248, 2024).
HIV-1 infection (2 papers, 2013 to 2016). The type species of lentivirus and the etiologic agent of acquired immunodeficiency syndrome (AIDS). "In agreement with this, dysregulation of B cells in HIV-1 infection has been associated with decreased BTLA expression on these cells in viremic individuals compared to aviremic individuals and healthy controls." (PMID 23514593, 2013). "Although BTLA has been proposed to be a negative regulator of T-cell activation, its potential inhibitory function is still inconclusive in HIV-1 infection." (PMID 23514593, 2013). "Our studies showed that BTLA upregulation was indistinctive on HIV-infected T cells in vitro while others have reported that HIV-1 infection could downregulate BTLA on CD4+ and CD8+ T cells." (PMID 23514593, 2013).
Lewis lung carcinoma (2 papers, 2025). "To investigate whether BTLA is involved in resistance to PD-1/PD-L1 blockade therapy, we performed in vivo treatment with PD-1/PD-L1 antibodies in Lewis lung carcinoma (LLC)-derived murine NSCLC model." (PMID 40463377, 2025). "In vivo treatment experiments demonstrated that anti-BTLA immunotherapy reinvigorated antitumor immunity in TME, resulting in enhanced tumor inhibition and survival improvement in FXRhiPD-L1lo mouse Lewis lung carcinomas." (PMID 40985894, 2025).
metastasis (2 papers, 2021 to 2022). The spread or migration of cancer cells from one part of the body (where they first appeared) to another. "The key immune checkpoints including BTLA, CD86, CD244, and PDCD1 are recognized as predictors of sentinel lymph node metastasis in cutaneous melanoma." (PMID 35069935, 2022).
multiple sclerosis (2 papers, 2016 to 2021). A progressive autoimmune disorder affecting the central nervous system resulting in demyelination. "The number of BTLA-expressing B cells and CD19+/BTLA+/IL-10+ cells obviously decreased in multiple sclerosis (MS) cases, while the remission of fingolimod-induced relapsed-remitted MS is related to a significantly increased number of CD19+/BTLA+/IL-10+ B lymphocytes." (PMID 33859648, 2021).
Neonatal sepsis (2 papers, 2023 to 2025). Systemic inflammatory response to infection in newborn babies. "Targeting BTLA may be a new strategy for treating neonatal sepsis." (PMID 41209006, 2025).
oral cancer (2 papers, 2021 to 2024). "At both mRNA and protein levels, there was a highly significant association between increased expression of BTLA (above a calculated cut-off point) and the diagnosis of oral cancer in a given tissue sample." (PMID 38928307, 2024). "The results of the current study show that BTLA expression is upregulated in oral cancer." (PMID 38928307, 2024). "In addition, the expression of BTLA protein was remarkably increased in oral cancer tissues compared to healthy mucosa specimens in the epithelial compartment." (PMID 38928307, 2024). "The low expression of three ICGs positively correlated with CD274 (BTLA, CD27, and CTLA4) indicated a better prognosis compared to their high expression, indicating their coinhibitory roles in the tumor immunology of oral cancer." (PMID 35127742, 2021). "The significant positive correlation between BTLA expression and other immune checkpoints including CD96 and PD1 with its ligands indicate that BTLA-inhibition in oral cancer might be promising, especially in the form of a combination immunotherapy." (PMID 38928307, 2024). "Hence, the data highlight the expression of BTLA in oral cancer and motivate clinical trials of anti-BTLA therapy—preferentially as a concept of a simultaneous therapeutic targeting of multiple inhibitory signalling pathways like PD1, CD96 and BTLA—in oral cancer." (PMID 38928307, 2024).
Pleural effusion (2 papers, 2021 to 2022). The presence of an excessive amount of fluid in the pleural cavity. "An analogous finding showed that high co-expression of BTLA and B7-H4 on myeloid dendritic cells (mDCs) in peripheral blood and pleural effusions of pleural TB patients promoted a high level of CD83 and HLA-DR, which had a negative regulatory effect on mDCs and anti-TB immunity." (PMID 34163466, 2021).
pneumonia (2 papers, 2021 to 2023). An acute, acute and chronic, or chronic inflammation focally or diffusely affecting the lung parenchyma, caused by an infection in one or both of the lungs (by bacteria, viruses, fungi, or mycoplasma.). "One study focused on pneumonia demonstrated that BTLA protein expression was mainly present in the bronchial epithelium and inflammatory cells in patients with severe community-acquired pneumonia (CAP), suggesting that BTLA might be involved in host protection." (PMID 34163466, 2021).
pulmonary tuberculosis (2 papers, 2021). A bacterial infection that affects the lungs and is caused by Mycobacterium tuberculosis. "Moreover, active pulmonary tuberculosis drives BTLA expression in DCs, thereby inhibiting Th17 and Th22 responses induced by DCs and promoting Treg and Th2 differentiation." (PMID 33859648, 2021). "Similarly, BTLA levels increase in CD4+ and CD8+ T cells from patients with pulmonary tuberculosis, and this is related to disease progression." (PMID 33859648, 2021).
Shock (2 papers, 2015 to 2018). The state in which profound and widespread reduction of effective tissue perfusion leads first to reversible, and then if prolonged, to irreversible cellular injury. "Soluble BTLA levels were assessed in the lungs, BAL fluid and serum of mice with severe critical illness induced by hemorrhagic shock followed by septic shock." (PMID 30134817, 2018).
small cell lung carcinoma (2 papers, 2024 to 2025). Small cell lung cancer (SCLC) is a highly aggressive malignant neoplasm, accounting for 10-15% of lung cancer cases, characterized byrapid growth, and early metastasis. "In addition, a phase III study with a total of 756 participants is planned to test the clinical efficiency of combined anti-BTLA and anti-PD1 ICI therapy as adjuvant treatment for early-stage small cell lung cancer after initial radiochemotherapy (NCT06095583)." (PMID 38928307, 2024).
systemic inflammatory response syndrome (2 papers, 2013 to 2014). SIRS is a serious condition related to systemic inflammation, organ dysfunction, and organ failure. "Changes in CD4+ lymphocyte BTLA expression were compared with morbid event development in critically ill ICU patients (11 septic and 28 systemic inflammatory response syndrome subjects)." (PMID 24289156, 2013). "In 11 septic ICU patients, a significantly higher percentage of circulating lymphocytes expressing BTLA was found, compared with patients with nonseptic systemic inflammatory response syndrome (SIRS)." (PMID 25673430, 2014).
thyroid carcinoma (2 papers, 2020 to 2021). "Overall, we observed significant association between IGSF10 and immune checkpoint genes such as CD200R1, VSIR, CD160, CD28, BTLA, and CD40LG in several tumors including low-grade glioma (LGG) and thyroid carcinoma (THCA)." (PMID 34351868, 2021).
acute lymphoblastic leukemia (1 paper, 2016). Leukemia with an acute onset, characterized by the presence of lymphoblasts in the bone marrow and the peripheral blood. "Interestingly, the BTLA/CD200 deletions have recently been reported in adult B cell precursor acute lymphoblastic leukemia (ALL) pts." (PMID 27933341, 2016).
AIDS (1 paper, 2022). A syndrome resulting from the acquired deficiency of cellular immunity caused by the human immunodeficiency virus (HIV). "Lower expression of BTLA on both T cells and HIV-specific CD8+ T cells was commonly found in HIV-infected patients either as TP or with AIDS, but rarely found in LTNP." (PMID 35336991, 2022). "Given that only clinical trial data for PD-1 and CTLA-4 blockers are available, the data from testing blockers against other ICs (TIGIT, LAG-3, Tim-3, CD160, 2B4, BTLA, and VISTA) may prove highly useful in treatment of AIDs." (PMID 35336991, 2022).
autoimmune encephalitis (1 paper, 2017). Inflammation of the brain secondary to an immune response triggered by the body itself. "Consistent with a role of BTLA in maintaining peripheral tolerance, BTLA-deficient mice have increased susceptibility to experimental autoimmune encephalitis, whereas induction of oral tolerance is also compromised." (PMID 28443090, 2017).
esophageal cancer (1 paper, 2016). A primary or metastatic malignant neoplasm involving the esophagus. "Above results showed that PD-1, TIM-3, TIGIT and BTLA expressions were dysregulated on a fraction of peripheral blood T cells of esophageal cancer patients." (PMID 27577071, 2016). "The MFI of BTLA on CD4+ and CD8+ TILs was lower than that of circulating CD4+ and CD8+ T cells from esophageal cancer patients." (PMID 27577071, 2016). "We next assessed the expressions of PD-1, TIM-3, TIGIT and BTLA on CD4+ and CD8+ T cells isolated from esophageal cancer tissues, adjacent esophageal mucosa (AEM), and peripheral blood mononuclear cell (PBMC) from esophageal cancer patients." (PMID 27577071, 2016).
immune deficiencies (1 paper, 2022). "Six genes related to (a) immune checkpoints (n = 2; BTLA and CD6); (b) regulatory macrophages and T cells (n = 2; CCR7 and CD3D); and (c) immune deficiencies and unfavorable prognosis (n = 2; CD3E and FCGR2B) were down-regulated post-RT compared with pre-RT (statistical p-range: <0.0001–0.0415)." (PMID 36291815, 2022).
kidney cancer (1 paper, 2021). Primary or metastatic malignant neoplasm involving the kidney. "In another study, rs1982809 polymorphism of the BTLA was found to be associated with the risk of kidney cancer." (PMID 33564688, 2021).
large-cell lymphoma (1 paper, 2023). "In large-cell lymphoma, BTLA+ T cells are less differentiated and have impaired killing capacity." (PMID 37443727, 2023).
lupus nephritis (1 paper, 2019). Glomerulonephritis in the context of systemic lupus erythematosus. "The expression of BTLA on stimulated Th17-cells in SLE patients with lupus nephritis as compared to SLE patients without lupus nephritis was not significantly different (44.7% ± 32.2% vs. 22.6% ± 12.9%, p = 0.34)." (PMID 31514450, 2019). "The expression of BTLA on Th1, Th2, and Th17 effector T-cells was investigated in patients with and without lupus nephritis." (PMID 31514450, 2019). "The aim of this study was to investigate BTLA expression on regulatory and effector CD4+ T-cells in SLE patients with and without lupus nephritis (LN) during active and inactive disease." (PMID 31514450, 2019).
lymphopenia (1 paper, 2019). Reduction in the number of lymphocytes. "We identified a specific CHIKV signature composed of 107 down-regulated genes that includes CX3CR1, BTLA, BCL2, GZMK and three genes that encode Fc receptor-like glycoproteins that could be related to the lymphopenia induced by CHIKV infection." (PMID 31211814, 2019).
mesothelioma (1 paper, 2023). A usually malignant and aggressive neoplasm of the mesothelium which is often associated with exposure to asbestos. "In this consideration, besides anti-PD-1, other immune checkpoint inhibitors such as anti-BTLA, anti-CTLA-4, anti-Siglec-10, anti-TIGIT, anti-TIM-3, anti-LAG-3 could be tested in combination to investigate their suitability for enhancing Vδ2 T cell efficacy in this mesothelioma model." (PMID 38077396, 2023).
metastatic tumors (1 paper, 2021). "Immune inhibitors like PD-1, BTLA and CTLA-4 were significantly highly expressed in metastatic tumors with reduced neoantigens, which further supported that reduction of neoantigens was associated with functional deficiency of immune cells." (PMID 33995666, 2021).
Moyamoya disease (1 paper, 2023). Moyamoya disease (MMD) is a rare intracranial arteriopathy involving progressive stenosis of the cerebral vasculature located at the base of the brain causing transient ischemic attacks or strokes. "The BTLA-TNFRSF14 pathway identified by us may be a potential target for the treatment of Moyamoya disease." (PMID 37400835, 2023).
myasthenia gravis (1 paper, 2019). Myasthenia gravis (MG) is a rare, clinically heterogeneous, autoimmune disorder of the neuromuscular junction characterized by fatigable weakness of voluntary muscles. "A previous study indicated that the up-regulation of BTLA gene expression and soluble BTLA (sBTLA) was validated in thymoma-associated myasthenia gravis." (PMID 31774112, 2019).
myositis (1 paper, 2022). "Increased IL-1α, IL-21, LIF, and PlGF-1 levels were significantly associated with the incidence of myositis, and the serum levels of six cytokines (BTLA, GM-CSF, IL-4, PD-1, PD-L1 and TIM-3) were higher in patients who developed a rash." (PMID 36159840, 2022). "Increased IL-1α, IL-21, LIF, and PIGF-1 levels were significantly associated with myositis incidence, while the serum levels of six cytokines (BTLA, GM-CSF, IL-4, PD-1, PD-L1 and TIM-3) were higher in patients with rash." (PMID 36159840, 2022).
ocular infection (1 paper, 2020). "To further assess the contribution of HVEM binding partners in disease severity, we used a Luneau Cochet-Bonnet esthesiometer to measure the blink response in BTLA−/−, LIGHT−/−, and CD160−/− mice following HSV-1 ocular infection." (PMID 32398314, 2020).
pancreatic ductal adenocarcinoma (1 paper, 2023). An infiltrating adenocarcinoma that arises from the epithelial cells of the pancreas. "In liver metastases from primary pancreatic ductal adenocarcinoma, CD200 and BTLA pathways can drive macrophage-mediated adaptive immune tolerance." (PMID 37143720, 2023).
papillary renal cell carcinoma (1 paper, 2024). A rare subtype of renal cell carcinoma, arising from the renal tubular epithelium and showing a papillary growth pattern, which typically manifests with hematuria, flank pain, palpable abdominal mass or nonspecific symptoms, such as fatigue, weight loss or fever. "An analysis utilizing the BTLA TIMER Database uncovered an interesting trend: in Papillary Renal Cell Carcinoma (PRCC), BTLA expression is notably higher in cancer cells than in the adjacent healthy tissues." (PMID 39796121, 2024). "This unique expression pattern suggests that BTLA mRNA levels are significantly elevated in PRCC, positioning it as a valuable marker for diagnosing and predicting Papillary Renal Cell Carcinoma." (PMID 39796121, 2024).
periodontitis (1 paper, 2022). An acute or chronic inflammatory process that affects the tissues that surround and support the teeth. "In the intercellular network, BTLA and IFNG signals are strongly activated in the circulatory system during periodontitis." (PMID 36329504, 2022). "In addition, activated cell type-specific ligand-receptor interactions, including the BTLA, IFN-γ, and RESISTIN pathways, were prominent in patients with periodontitis." (PMID 36329504, 2022).
Psoriasiform dermatitis (1 paper, 2017). A skin abnormality characterized by redness and irritation, with thick, red skin that displays flaky, silver-white patches (scales). "PD-1 and BTLA knockout mice developed more severe psoriasiform dermatitis in the IMQ model." (PMID 28469254, 2017).